GGH (gamma-glutamyl hydrolase)
Diseases named in the same sentence as GGH in open-access papers (continued):
Sharing a sentence is not in itself a finding about the gene and the disease.
acute lymphoblastic leukemia (2 papers, 2016 to 2017). Leukemia with an acute onset, characterized by the presence of lymphoblasts in the bone marrow and the peripheral blood. "The VAR status of GGH_452T/C was found in children with acute lymphoblastic leukemia who showed exclusively low or intermediate catalytic activity of GGH with the consequence of intracellular accumulation of long-chain methotrexate polyglutamates." (PMID 27566557, 2016). "In addition to genetic polymorphism and karyotypic abnormalities, methylation of CpG island 1 (CpG1) in the promoter region is found to modulate GGH activity by reducing GGH mRNA expression in acute lymphoblastic leukemia (ALL) cells." (PMID 28278270, 2017).
depression (2 papers, 2020 to 2023). "Moreover, among the 18 depression causal genes with sex-biased protein expression that we identified, GGH and PRKAR2A are implicated in immune response." (PMID 37653343, 2023).
lung adenocarcinoma (2 papers, 2020 to 2025). A carcinoma that arises from the lung and is characterized by the presence of malignant glandular epithelial cells. "In lung adenocarcinoma, the GGH expression was lower and correlated with higher folate concentrations and increased DNA methylation." (PMID 33036472, 2020). "Although GGH has been reported to play varying roles in different cancer types, with potentially distinct biological functions, its role in lung adenocarcinoma (LUAD) remains unclear." (PMID 40268350, 2025). "In this study, we found that GGH functions as a crucial oncogene in lung adenocarcinomas." (PMID 40268350, 2025).
lung carcinoma (2 papers, 2025). "Here, it is reported that GGH silencing inhibited the growth of lung cancer cells in vivo and in vitro." (PMID 40831251, 2025). "GGH was also highly expressed in lung cancer tissues and its higher expression was correlated to poor patient survival in lung cancer." (PMID 40831251, 2025). "Beyond lung cancer, knockdown of GGH could result in the activation of the ULK1 complex and PI3KC3-C1 via the phosphorylation of ULK1 and PIK3C3 in a multitude of cancer cell lines." (PMID 40268350, 2025). "In summary, GGH has an oncogenic role in lung cancer progression, which may act as an RNA‐binding protein together with HuR protein in the regulation of cell cycle and DNA replication processes." (PMID 40831251, 2025). "Finally, it is found that GGH is highly expressed in lung cancer tissues, and its elevated expression correlates with worse patient survival in lung cancer." (PMID 40831251, 2025). "To explore more functions and mechanisms of GGH in lung cancer progression, we performed RNA‐seq and DIA‐MS analysis upon GGH silencing by siRNAs in NSCLC cell lines." (PMID 40831251, 2025).
psoriasis (2 papers, 2009 to 2020). An autoimmune condition characterized by red, well-delineated plaques with silvery scales that are usually on the extensor surfaces and scalp. "Besides, some psoriasis-related genes such as SPRR genes, HSD11B1, GGH, CXCR2, IVL, OASL, ISG15, and CXCL10 may be important targets in psoriatic therapy." (PMID 32669126, 2020). "We conclude that genetic variation across the genes FPGS, GGH, MTHFR and ATIC is not predictive of either efficacy or toxicity of methotrexate in patients with psoriasis." (PMID 19016697, 2009).
pulmonary TB (2 papers, 2015 to 2024). "Four proteins, FCGR3B, FETUB, GGH, and SERPIND1, were present at significantly higher levels in the serum of pulmonary TB patients than both HCs and ORI cases, thereby exhibiting a high degree of specificity for TB." (PMID 38512356, 2024). "All the proteins such as GGH, IGHG3 and HPT were closely related to the body’s metabolism, immune function and pulmonary TB." (PMID 26198726, 2015).
thymic carcinoma (2 papers, 2019 to 2020). Thymic carcinoma (TC) is a type of thymic epithelial neoplasm characterized by a high malignant potential. "In addition, increased expression of tumor-associated genes, such as FPGS (folylpolyglutamate synthase)/GGH (gamma-glutamyl hydrolase) and VEGF (vascular endothelial growth factor), were found to be related to the degree of malignancy in thymic carcinoma and B3 thymoma." (PMID 32993581, 2020).
urothelial carcinoma of the bladder (2 papers, 2013 to 2017). "In urothelial carcinoma of the bladder, elevated level of GGH was also detected in cancerous cells in comparison with non-cancerous cells." (PMID 23374458, 2013).
acute myeloid leukemia (1 paper, 2021). Acute myeloid leukemia (AML) is a group of neoplasms arising from precursor cells committed to the myeloid cell-line differentiation. "Further, GGH expression was also elevated in adrenocortical carcinoma, diffuse large B cell lymphoma, acute myeloid leukemia, brain lower grade glioma, ovarian serous cystadenocarcinoma, and uterine carcinosarcoma, as evidenced by comparison to normal tissues from the combined GTEx and TCGA dataset." (PMID 35082830, 2021).
asthma (1 paper, 2021). "However, the relationship between GGH and asthma has not yet been characterized, which requires further investigation." (PMID 34336929, 2021). "However, there were no reports, so far, on the roles of BPIFA1, GGH, hsa-miR-30a-3p, hsa-miR-30d-3p, hsa_circ_0001585, hsa_circ_0078031, and hsa_circ_0000552 in asthma." (PMID 34336929, 2021).
atopic dermatitis (1 paper, 2026). "Our findings establish a causal relationship between specific gut bacteria (Eubacterium eligens group) and atopic dermatitis risk while identifying seven key bridging genes (AKR1C2, GALE, GGH, NR4A1, PLA2G4B, TYMS) that connect gut microbial metabolites to skin pathology." (PMID 41556698, 2026).
Burkitt lymphoma (1 paper, 2020). A rare form of malignant mature B-cell non-Hodgkin lymphoma. "We evaluated cell viability after MTX treatment and leucovorin rescue and compared the expression of folylpolyglutamate synthetase (FPGS), γ-glutamyl hydrolase (GGH), and DHFR in 2 human PCNSL-derived cell lines (HKBML and TK) and a human Burkitt lymphoma cell line (TL-1)." (PMID 32793886, 2020).
hepatoma (1 paper, 2013). "High GGH expression level was also detected in hepatoma cells compared with rat hepatocytes." (PMID 23374458, 2013).
hyperplastic polyp (1 paper, 2008). A polyp found mainly in the stomach and colon. "Further studies are required in which GGH expression, folate status and CpG island methylation are evaluated in normal colonic tissue as well as in the proposed precursor lesion for CIMP+, the so-called serrated adenoma or hyperplastic polyp." (PMID 18414409, 2008).
idiopathic thrombocytopenic purpura (1 paper, 2017). "In addition, without methylation in CpG1 or CpG2, GGH mRNA abundances in cells from bone marrow of ALL, AML and idiopathic thrombocytopenic purpura (ITP) control patients are significantly higher than that in peripheral blood of healthy control patients (p<0.05)." (PMID 28278270, 2017).
malabsorption syndrome (1 paper, 2018). A syndrome resulting from the inadequate absorption of nutrients in the small intestine. "This genetic variant is associated with GGH gene expression, which was previously implicated as involved in the pathogenesis of tropical sprue, a malabsorption syndrome commonly found in tropical regions." (PMID 29580271, 2018).
Mycobacterium infection (1 paper, 2015). Infections with bacteria of the genus Mycobacterium. "GGH was associated with folate metabolism in PYD cases, IGHG3 was linked to the control of Mycobacterium infection in HFYD patients, and HPT was involved in hypoxia in DQY patients." (PMID 26198726, 2015). "GGH was associated with folate metabolism in PYD patients, and IGHG3 was linked to the control of Mycobacterium infection in HFYD patients." (PMID 26198726, 2015).
myeloma (1 paper, 2020). "The relative mRNA expression levels of four folate pathway genes (RFC, GGH, FPGS and DHFR) were examined in eight myeloma cell lines, including four resistant lines (ARP-1, CAG, RPMI 8228, U266) and four sensitive lines (ARH-77, KMS-11, MM.1s, PCNY-1B)." (PMID 32405334, 2020).
Obesity (1 paper, 2020). Accumulation of substantial excess body fat. "Gamma glutamyl-hydrolase is an enzyme involved in folate metabolism, while lower folates levels were associated with reduced insulin sensitivity and obesity." (PMID 32635923, 2020).
oral squamous cell carcinoma (1 paper, 2019). "In oral squamous cell carcinoma, GGH is a member of an 11 gene molecular signature with a worse overall survival maker for patients without nodal metastases." (PMID 31105744, 2019).
pituitary tumor (1 paper, 2024). A benign or malignant neoplasm affecting the pituitary gland. "Through rigorous functional validations, we observed that both GGH and PBK significantly inhibited pituitary tumor cell apoptosis and enhanced cell proliferation." (PMID 38167466, 2024).
pulmonary neuroendocrine tumors (1 paper, 2013). "The elevated levels of GGH were reported to be correlated with poor clinical outcome in pulmonary neuroendocrine tumors." (PMID 23374458, 2013).
rectal cancer (1 paper, 2017). A primary or metastatic malignant neoplasm that affects the rectum. "Therefore, the gene expression levels of four genes, HIF1A, MTHFD1, GGH and TYMS, in tumor tissues before CRT may be useful for predicting the efficacy of preoperative CRT including S-1 or UFT/LV in patients with rectal cancer." (PMID 28417167, 2017).
staphylococcus aureus infection (1 paper, 2021). An infectious process in which the bacteria Staphylococcus aureus is present. "Additionally, KEGG analysis showed that GGH-interactive genes also included those related to “Staphylococcus aureus infection” and “olfactory transduction”." (PMID 35082830, 2021).
tumor (24 papers, 2008 to 2025). "Overexpression of GGH has been implicated in many diseases, and high expression and abnormal activity have been detected in multiple cancer cell lines and tumor tissues." (PMID 35082830, 2021). "Collectively, these findings suggest that GGH overexpression contributes directly or indirectly to biological processes underlying tumor aggression and hence poor outcome." (PMID 35082830, 2021). "Both GGH mRNA and protein expression levels were elevated in tumor tissues, and higher expression was significantly associated with advanced clinicopathological features and poor prognosis by univariate analysis." (PMID 35082830, 2021). "These associations between GGH expression and tumor clinical characteristics were weaker in the subset of ERG-positive cancers." (PMID 28146062, 2017). "Here, high-level GGH expression was strongly linked to advanced pathological tumor stage (p = 0.0016) and high Gleason grade (p < 0.0001), albeit the differences in absolute numbers between subgroups were not large." (PMID 28146062, 2017). "The significant association found in this study between GGH expression and rapid tumor cell proliferation supports this concept." (PMID 28146062, 2017). "Low GGH expression is associated with higher folate levels, leading to the enhancement of anti-tumor activity in 5-FU with LV." (PMID 26311588, 2015). "GGH protein expression was significantly associated with high histological tumor grade (BRE grade III, P < 0.001), and ER/PR receptors (P = 0.01)." (PMID 23374458, 2013). "Univariate analysis (Mann–Whitney U-test) showed that ECGF1 and GGH expressions were strongly associated with the CIMP+ features of proximal tumour site, TILs and BRAF mutation." (PMID 18414409, 2008). "High GGH activity has been associated with the resistance of tumour cell lines to MTX via shortening of polyglutamate chains and consequently a lower intracellular drug concentration and less inhibition of dihydrofolate reductase and TS." (PMID 18414409, 2008). "This tumour phenotype is associated with low expression of GGH, suggesting involvement of the folate pathway in its development and/or growth." (PMID 18414409, 2008). "It remains unclear whether GGH functions as an oncogene and its underlying mechanisms in tumor progression." (PMID 40831251, 2025). "Further, GGH expression was associated with greater tumor progression and poorer outcome." (PMID 35082830, 2021). "Interestingly some marker (e.g., EFNA4, GGH) also depicted over-expression in other cancers indicating their association with tumor development and progression related hallmark processes." (PMID 33133160, 2020). "Higher GGH activity has been associated with 5-FU resistance in several tumor entities." (PMID 28146062, 2017). "Up-regulation of GGH has been described to occur in several neoplasias, including breast and colon cancers, pulmonary neuroendocrine tumors, and hematological cancers, and has been linked to adverse tumor features and poor clinical outcome in some of them." (PMID 28146062, 2017). "Both strategies effectively suppressed tumor growth in vivo, further confirming the critical role of GGH in tumorigenesis." (PMID 40831251, 2025). "Subsequent immunohistochemistry (IHC) staining of the xenografted tumor tissues demonstrated that shGGH effectively knocked down GGH expression, suppressed p62 level, and promoted p-AMPK and p-CAMKK2 levels." (PMID 40268350, 2025). "We further investigated strategies to impede tumor growth in mice by knocking down GGH expression and utilizing a specific inhibitor, azaserine." (PMID 40831251, 2025). "Despite its canonical role in inhibiting DNA synthesis, GGH promotes tumor growth as a novel RNA‐binding protein." (PMID 40831251, 2025). "This correlation was weaker in adjacent non‐cancerous tissues, suggesting that GGH was involved in the cell cycle and DNA replication in both cancer cell lines and tumor tissues." (PMID 40831251, 2025).
tumor (continued). "The results showed that shGGH effectively knocked down GGH expression and inhibited the proliferation of tumor cells in vivo." (PMID 40831251, 2025). "Our findings indicated that GGH functions more effectively as an RNA‐binding protein in tumor cells, promoting the smooth progression of the cell cycle and DNA replication." (PMID 40831251, 2025). "Relative to Post-OP levels, 64 uEV proteins changed significantly at GBM tumour recurrence (p ≤ 0.05), including three proteins (GGH, GRN, ITM2B) that increased by ≥2-fold in the REC group (adjust p-val≤0.05)." (PMID 38212481, 2024). "GGH upregulation decreased the tumor volume and weight, while its downregulation had the opposite effect." (PMID 36569910, 2022). "The results showed lower FPGS and higher GGH expression in tumor and mucosa of patients receiving two-hour infusion compared to bolus injection of LV, indicating that infusion of LV resulted in shorter polyglutamation chains of MeTHF than bolus injection." (PMID 36612253, 2022). "Differential gene expression between the high and low GGH expression groups was analyzed to identify potential downstream and upstream pathways regulating tumor progression and outcome." (PMID 35082830, 2021). "Mean GGH mRNA expression was also higher in UCEC tumor tissues compared to adjacent normal tissues from TCGA database and in UCEC tissues versus normal tissues from the combined GTEx and TCGA dataset (both p < 0.001)." (PMID 35082830, 2021). "To study the potential pathogenic functions of GGH in UCEC, we first compared GGH expression between tumor tissues and paracancerous tissues from 31 UCEC patients by immunohistochemistry." (PMID 35082830, 2021). "Denser immunostaining for GGH was observed in the cytoplasm of tumor cells, and H-scores indicated significantly higher immunoexpression in tumor tissues compared to paired paracancerous tissues (p = 0.0027) and unpaired control tissues (p = 0.0259)." (PMID 35082830, 2021). "Immunohistochemical results from the Human Protein Atlas also showed higher GGH expression in UCEC tumor tissues compared to normal tissues." (PMID 35082830, 2021). "We used the datasets in GEO to verify the ability of GGH expression levels to distinguish tumor tissues from non-tumor tissues, and the AUC was 0.711." (PMID 35082830, 2021). "High GGH expression was linked to the TMPRSS2:ERG-fusion positive subset of cancers (p < 0.0001), advanced pathological tumor stage, and high Gleason grade (p < 0.0001 each)." (PMID 28146062, 2017). "Overall, these data suggest that tumor-relevant functions of GGH and other proteins can become attenuated or amplified in an ERG-positive molecular environment." (PMID 28146062, 2017). "In tumor tissues, the mRNA expression of GGH was increased specifically in patients with short-term survivor." (PMID 23374458, 2013). "Due to loss of biopsy cores, insufficient tumor cells present in the cores or affluence of necrotic tissue, 72 FFPE specimens out of the collected 80 FFPE specimens were evaluated for GGH, FAAH, PIR and TAF5L immunostaining." (PMID 23374458, 2013). "Among the tumor tissues 75% (54/72) of the cases showed positive expression of GGH (χ2 = 17.9, P < 0.001)." (PMID 23374458, 2013). "In tumor tissue samples, seventy-one percent of the tumors had positive expression of GGH and FAAH simultaneously." (PMID 23374458, 2013). "Perhaps surprisingly, GGH (gamma-glutamyl hydrolase) expression also appeared to be increased in tumor samples versus normal tissue." (PMID 23880844, 2013). "An alternate explanation involving transcriptional silencing of GGH by promoter methylation was excluded by the finding that only 5.6% of CIMP+ tumours showed GGH hypermethylation." (PMID 18414409, 2008). "The results confirmed the previous result that GGH mRNA expression was significantly lower in CIMP+ CRC samples from a separate tumour series (P=0.0012)." (PMID 18414409, 2008).